SHANK3 (SH3 and multiple ankyrin repeat domains 3)
Diseases named in the same sentence as SHANK3 in open-access papers (continued):
Sharing a sentence is not in itself a finding about the gene and the disease.
Angelman syndrome (4 papers, 2019 to 2024). A neurogenetic disorder characterized by severe intellectual deficit and distinct facial dysmorphic features. "These are often observed in neurons derived from individuals with idiopathic forms of ASD, as well as from individuals with genetically defined forms of ASD such as SHANK3, 16p11.2 deletion and duplication, Angelman syndrome, Dup15q syndrome, NRXN1 mutations, and PTCHD1-AS." (PMID 32299488, 2020).
lymphedema (4 papers, 2013 to 2024). Excess fluid collection in tissues, causing swelling. "Lymphedema, cellulitis, precocious or delayed puberty, hearing problems, and hypothyroidism have been reported in cases with 22q13 deletions but were not present in individuals with SHANK3 mutations." (PMID 29719671, 2018).
neuroblastoma (4 papers, 2018 to 2023). Neuroblastoma (NB) is the most common solid, extracranial childhood tumor. "In order to validate that nNOS plays a key role in the pathology, we knocked down the expression of SHANK3 and nNOS in differentiated neuroblastoma cells." (PMID 37212048, 2023). "Furthermore, oxytocin has recently been shown to stimulate neurite outgrowth and increase gene expression of Shank3 protein in human neuroblastoma cells and to reverse neurite abnormalities in Shank3-deficient mice." (PMID 34593045, 2021).
amyotrophic lateral sclerosis (3 papers, 2022 to 2025). Amyotrophic lateral sclerosis (ALS) is a neurodegenerative disease characterized by progressive muscular paralysis reflecting degeneration of motor neurons in the primary motor cortex, corticospinal tracts, brainstem and spinal cord. "As an illustration, an aberrant relative abundance of alternatively spliced RNA isoforms of the SNCA, SRRM2, DAO, SHANK3, CACNA1C, and TSC2 genes has been observed in the brains of patients suffering from amyotrophic lateral sclerosis, autism spectrum disorder, and Parkinson’s disease." (PMID 39858933, 2025).
Down syndrome (3 papers, 2014 to 2023). "Adding to these co-existing conditions are rare genetic disorders and disorders of known etiology, like Down Syndrome, SHANK3 deletion syndrome, Fragile X, various forms of Cerebral Palsy, just to name a few." (PMID 37600235, 2023).
Parkinson disease (3 papers, 2025 to 2026). A progressive degenerative disorder of the central nervous system characterized by loss of dopamine producing neurons in the substantia nigra and the presence of Lewy bodies in the substantia nigra and locus coeruleus. "TAF1 and DPM2 provide potential clues about parkinsonism and increased creatine phosphokinase in neuroleptic malignant syndrome, while abnormalities in RALGPS1 suggest links to both anti-NMDAR antibody encephalitis and the SHANK3 gene, which is known to predispose to catatonia." (PMID 40400398, 2025).
autoimmune disease (2 papers, 2024 to 2025). A disorder resulting from loss of function or tissue destruction of an organ or multiple organs, arising from humoral or cellular immune responses of the individual to their own tissue constituents. "Furthermore, intermediate analyses revealed that air pollutants increased the risk of autoimmune diseases by modulating the expression of POR, HSPA1B, SHANK3, and BRD2." (PMID 38685026, 2024). "Then, we performed mediation analyses, which showed that POR, HSPA1B, SHANK3, and BRD2 might exert mediating effects from air pollutants to increased risk of autoimmune diseases." (PMID 38685026, 2024).
Cowden syndrome (2 papers, 2020 to 2024). "Variants in SHANK3 can accompany Phelan–McDermid syndrome; PTEN, Cowden syndrome; NSD1, Sotos syndrome; and RAI1, Smith–Magenis syndrome." (PMID 32477112, 2020).
gastroesophageal reflux (2 papers, 2013 to 2022). "Analyses of individuals with small deletions or point mutations identified features related to SHANK3 haploinsufficiency, including ASD, seizures and abnormal EEG, hypotonia, sleep disturbances, abnormal brain MRI, gastroesophageal reflux, and certain dysmorphic features." (PMID 23758760, 2013).
hyperkinetic disorders (2 papers, 2017 to 2018). "SHANK3 duplications have been identified in patients with hyperkinetic disorders and early-onset generalized tonic-clonic seizures." (PMID 30305163, 2018). "However, importantly, it needs to be validated whether the SHANK3 duplication patients with mania-like hyperkinetic disorders indeed express higher Shank3 protein levels." (PMID 28701918, 2017). "Indeed, we could also identify several patients with SHANK3 gene duplications who were diagnosed with mania-like hyperkinetic disorders." (PMID 28701918, 2017).
infarct (2 papers, 2020 to 2023). "We assessed the potential for Shank3 to alleviate the post-infarction cardiac dysfunction." (PMID 32982797, 2020). "Nevertheless, both morphological (infarct size) and functional (echocardiographic parameters, including LV ejection fraction and fractional shortening) changes after MI were significantly aggravated in Shank3 knock-out mice, while they were alleviated in Shank3 overexpressing mice." (PMID 37187620, 2023).
insomnia (2 papers, 2022 to 2024). A sleep disorder characterized by difficulty in falling asleep and/or remaining asleep. "We have previously shown that male mice with a mutation in the high confidence ASD gene Shank3, Shank3∆C, recapitulate most aspects of the ASD insomnia phenotype." (PMID 39468684, 2024). "For instance, mouse models of ASD candidate gene Shank3 were found to have insomnia-related difficulties (i.e., long sleep onset), but no circadian abnormalities." (PMID 36192372, 2022).
myocardial infarction (2 papers, 2020 to 2023). Gross necrosis of the myocardium, as a result of interruption of the blood supply to the area, as in coronary thrombosis. "In addition, changes in cardiac morphology and function associated with myocardial infarction and aging have been investigated in a few Shank3 mutant mouse models." (PMID 37187620, 2023). "Another study demonstrated the effects of Shank3 dosage on the morphological and functional changes in the heart after myocardial infarction (MI) by investigating the phenotypes in adult Shank3 knock-out and overexpressing mice." (PMID 37187620, 2023).
Obesity (2 papers, 2021 to 2022). Accumulation of substantial excess body fat. "Similarly, genes encoding circadian clock regulators (Dbp, Nr1d1 and Nr1d2), KLF transcription factors (Klf2 and Klf6) and cell signaling molecules (Rhob and Shank3) were also upregulated in sustained obesity (cohort 2) but not in the reversion group (cohort 3)." (PMID 36400935, 2022).
viral infection (2 papers, 2016 to 2022). "The reduced Shank3 expression, locations of viral infection and NAC electrode placement were verified post mortem." (PMID 27161151, 2016).
Aicardi-Goutières syndrome (1 paper, 2022). "This has been previously observed in rare observational cohorts of individuals with rare genetic disorders that predispose toward immunotherapy-responsive neuroinflammation such as SHANK3 and Aicardi-Goutières syndrome." (PMID 35659536, 2022).
atherosclerosis (1 paper, 2023). A disease characterized by the build-up of fatty material and calcium deposition in the arterial wall resulting in partial or complete occlusion of the arterial lumen. "Therefore, in this study, we explored the role of Shank3 in atherosclerosis, which is the main cause of CVD." (PMID 37947623, 2023). "Therefore, the expression of Shank3 in endothelial cells may accelerate the development of atherosclerosis-associated CVD." (PMID 37947623, 2023). "Hence, understanding the molecular mechanisms underlying Shank3-related ASD may contribute to understanding the development of atherosclerosis in ASD." (PMID 37947623, 2023). "Together, the findings suggest that Shank3 knockdown plays a regulatory role in the development of atherosclerosis in individuals with ASD." (PMID 37947623, 2023). "Our findings indicate that Shank3, a leading ASD candidate gene, modulates the risk of atherosclerosis." (PMID 37947623, 2023). "Given that multiple investigations have reported a close relationship between CVD, hyperlipidemia, and ASD, we hypothesized that Shank3 associated with ASD can potentially contribute to the initiation and progression of atherosclerosis, the main cause of CVD." (PMID 37947623, 2023). "Shank3 may be involved in cholesterol homeostasis and fatty acid metabolism, potentially leading to atherosclerosis and CVD development." (PMID 37947623, 2023). "Because vascular cell adhesion molecule 1 (VCAM-1) plays a major role in atherosclerosis, we investigated whether Shank3 modulates the tumor necrosis factor-α (TNF-α)–induced expression of VCAM-1." (PMID 37947623, 2023). "In this study, we investigated whether Shank3 facilitates the development of atherosclerosis." (PMID 37947623, 2023). "Furthermore, regulating Shank3 expression may reduce inflammation-related disorders, such as atherosclerosis, by inhibiting tumor necrosis factor-alpha-mediated inflammatory cascades." (PMID 37947623, 2023). "Thus, Shank3 may influence the development of early-onset atherosclerosis and CVD in ASD." (PMID 37947623, 2023). "Therefore, the modulation of Shank3 expression may be associated with inflammation-related disorders, such as atherosclerosis, rather than only affecting the brain, through the suppression of TNF-α-mediated inflammation cascades." (PMID 37947623, 2023). "Therefore, the results suggest that Shank3 modulates the activities of signaling pathways (p38, JNK1, JNK2, and NF-κB) involved in the development of atherosclerosis-related inflammation." (PMID 37947623, 2023).
cardiac ischemia (1 paper, 2020). "Our study first reports the key role Shank3 plays in functional recovery after cardiac ischemia and hypoxia by promoting autophagy and inhibiting apoptosis." (PMID 32982797, 2020). "Thus, we hypothesized that Shank3 may also play an essential role in the process of cardiac ischemia and hypoxia." (PMID 32982797, 2020).
childhood disintegrative disorder (1 paper, 2015). A rare pervasive developmental disorder with a disease onset before the age of three and characterized by a dramatic loss of behavioral and developmental functioning after atleast two years of normal development. "In conclusion, we describe for the first time a partial deletion of the SHANK3 gene associated with a clinical profile of childhood disintegrative disorder or Heller’s syndrome." (PMID 26489495, 2015).
colon cancer (1 paper, 2015). "In this study, we report a novel interaction between the Mutated in colorectal cancer (MCC) protein and a newly identified SHANK3 protein isoform in human colon cancer cells and mouse brain tissue." (PMID 25997006, 2015). "Confocal microscopy also showed that endogenous MCC partially co-localizes with endogenous SHANK3 at the cell membrane of SW480 and HCT116 colon cancer cells." (PMID 25997006, 2015).
diabetic retinopathy (1 paper, 2023). "When investigating sub-phenotypes of T2DM, diabetic retinopathy has been identified to be associated with ACVRIC (rs4664229), ZFHX4 (rs61729527), WNT9B (rs4968281), SHANK3 (rs9616915), ZSCAN5A (rs7252603), and DCP1B (rs715146, rs1044950, rs113147414) gene." (PMID 37033211, 2023). "The association with pulse pressure and blood pressure have been associated to diabetic retinopathy through arterial stiffness and vision impairment, which has been identified in multiple genes, including the ZFHX4 gene, the SHANK3 gene, and the WNT9B gene." (PMID 37033211, 2023).
epilepsy syndrome (1 paper, 2026). A syndrome that has a characteristic cluster of clinical features and/or lectroencephalographic (EEG) findings that reflect underlying epileptic activity. "SHANK3 (22q13.33, OMIM#606230) pathogenic variants are associated with seizures in 60% of patients, with no specific epilepsy syndromes being reported." (PMID 41523187, 2026).
Fever (1 paper, 2023). Body temperature elevated above the normal range. "However, SHANK3 or/and TRPM2 play an important role in maintaining body temperature, under stressful conditions with temperature perturbations, such as LPS challenge, VNS by auricular application of menthol and capsaicin, cold environment, and PGE2-induced fever." (PMID 36845137, 2023).
generalized tonic-clonic seizures (1 paper, 2018). "Although the two SHANK3 duplication patients commonly showed generalized tonic-clonic seizures, the potential association between Shank3 overexpression and lethality, at least in Shank3 TG mice, has not been investigated in detail." (PMID 30305163, 2018).
heart failure (1 paper, 2020). Inability of the heart to pump blood at an adequate rate to meet tissue metabolic requirements. "Our results sheds light on a new research direction for cardiac remodeling and heart failure after MI, and Shank3 may also become a new therapeutic target for the diseases." (PMID 32982797, 2020).
injury (1 paper, 2024). Damage inflicted on the body as the direct or indirect result of an external force, with or without disruption of structural continuity. "The role of Shank3 has not been well characterised in microglia but is known to be chronically up regulated in expression following a traumatic brain injury and leads to a decreased gliosis response in Shank3 knockout mice." (PMID 38476460, 2024).
Insulin resistance (1 paper, 2019). Increased resistance towards insulin, that is, diminished effectiveness of insulin in reducing blood glucose levels. "Corticotropin releasing hormone binding protein (CRHBP), ARHGEF15, MME, MAP1A, FGF13, and SHANK3 are novel biomarkers for the development of insulin resistance." (PMID 30678306, 2019).
leukemia (1 paper, 2014). A malignant (clonal) hematologic disorder, involving hematopoietic stem cells and characterized by the presence of primitive or atypical myeloid or lymphoid cells in the bone marrow and the blood. "Herein we show that in leukemia cells ERG overexpression promotes a mesenchymal-like gene expression signature that includes: CD24, CD44, ITGA10, ITGB5, ITGB3, ITGA2B and the morphogenic-associated genes, such as SHANK3, TYROBP." (PMID 24504051, 2014).
liver cancer (1 paper, 2022). An epithelial or non-epithelial malignant neoplasm that arises from the liver. "There is also a significant gene in thyroid tissue, i.e., SHANK3, which is also under-expressed in liver cancer tissue." (PMID 35646080, 2022).
metachromatic leukodystrophy (1 paper, 2019). A rare lysosomal storage disorder characterized by intralysosomal accumulation of sulfatides in various tissues, leading to progressive deterioration of motor and neurocognitive function. "Patients with deletions extending proximal to SHANK3 have one missing copy of ARSA and may develop metachromatic leukodystrophy in the presence of a pathogenic mutation in the remaining ARSA allele." (PMID 31879555, 2019).
mood disorder (1 paper, 2015). A cognitive disorder a disturbance in which the person's mood is hypothesized to be the main underlying feature. "In addition to SHANK3, miR-504 also regulates the expression of the dopamine D1 receptor gene (DRD1), expression or activity of which is associated with multiple neuropsychiatric disorders including mood disorders." (PMID 26572867, 2015).
pneumonia (1 paper, 2013). An acute, acute and chronic, or chronic inflammation focally or diffusely affecting the lung parenchyma, caused by an infection in one or both of the lungs (by bacteria, viruses, fungi, or mycoplasma.). "Isolated reports have emerged recently describing significant medical complications of SHANK3 deficiency in the context of severe cognitive and behavioral regression, including seizure-induced aspiration, renal failure and pneumonia." (PMID 23758760, 2013).
respiratory infections (1 paper, 2023). "It is noteworthy that ASD children with SHANK3 mutations exhibit frequent respiratory infections in 57% cases." (PMID 36845137, 2023).
Senile plaques (1 paper, 2011). Senile plaques are extracellular deposits of amyloid in the gray matter of the brain. "Furthermore, in APP-PS1 mice and human AD brain sections, Zn2+ sequestration in senile plaques is accompanied by a decrease in intracellular Zn2+ concentration along with a decrease in synapse density and synaptic ProSAP2/Shank3 and Shank1 protein levels." (PMID 21939532, 2011).
Sepsis (1 paper, 2023). Sepsis is defined as life-threatening organ dysfunction caused by a dysregulated host response to infection. "Our findings demonstrated a novel molecular mechanism by which Shank3 in vagal sensory neurons regulates body temperature, inflammation, and sepsis." (PMID 36845137, 2023). "More strikingly, sepsis-induced hypothermia was significantly aggravated in both Shank3+/- and Shank3-/- mice (F = 48.24, p < 0.0001, two-way ANOVA)." (PMID 36845137, 2023). "Collectively, these data demonstrate that SHANK3 in Nav1.8-expressing peripheral sensory neurons confers protection against hypothermia, systemic inflammation and septic death after sepsis." (PMID 36845137, 2023). "We found that homozygous and heterozygous Shank3 deficiency, but not Shank2 and Trpv1 deficiency, aggravates hypothermia, systemic inflammation (serum IL-6 levels), and sepsis mortality in mice, induced by lipopolysaccharide (LPS)." (PMID 36845137, 2023). "Next, we investigated whether sepsis-induced systemic inflammation was altered in Shank3 mutant mice." (PMID 36845137, 2023). "Given a functional link between SHANK3 and TRPV1 in DRG primary sensory neurons and heat sensation, we evaluated whether peripheral TRPV1 is important for sepsis-induced hypothermia." (PMID 36845137, 2023). "However, we did not detect any difference of mortality between control siRNA and Shank3 siRNA treatment, as CD1 mice are more resistant to sepsis than C57BL/6 mice." (PMID 36845137, 2023).
Sleep disturbance (1 paper, 2019). An abnormal pattern in the quality, quantity, or characteristics of sleep. "Phenotypes specific for TCF20, such as sleep disturbances and movement disorders, may help clinically distinguish the 22q13.2 deletions from the 22q13.3 deletions (SHANK3)." (PMID 30819258, 2019).
Stroke (1 paper, 2024). Sudden impairment of blood flow to a part of the brain due to occlusion or rupture of an artery to the brain. "Notably, analysis of 341 DE mRNA associated with stroke (259 upregulated, 82 downregulated) in the IR group revealed upregulation of genes like Ccl2, Cxcl1, C3, Serpine1, Adamts7, Csf3, Ptx3, MMP8, Lif, and Lcn2, and downregulation of Gdf10, Agtr2 and Shank3." (PMID 39170713, 2024).
Thrombocytopenia (1 paper, 2023). A reduction in the number of circulating thrombocytes. "At the functional level, depletion of SVIL and SHANK3 inhibited megakaryopoiesis and thrombopoiesis, while overexpression of SVIL rescued the inhibitory effect of serine-mediated thrombocytopenia." (PMID 37055385, 2023).
upper respiratory tract infections (1 paper, 2013). "The presence of recurring ear and upper respiratory tract infections was notable and may reflect poor airway protection and sputum clearance due to low muscle tone in SHANK3 deficiency." (PMID 23758760, 2013).
vascular EDS (1 paper, 2025). "As approximately half of vascular EDS cases and the majority of SHANK3-related PMS cases arise from de novo variants, it is plausible that the dominant mutations identified in our patient occurred as de novo events, although this cannot be confirmed in the absence of parental testing." (PMID 40981013, 2025).